CRP (C-reactive protein)
Diseases named in the same sentence as CRP in open-access papers (continued):
Sharing a sentence is not in itself a finding about the gene and the disease.
Hypoalbuminemia (continued). "The AUC of CRP in preoperative period to the development of hypoalbuminemia on POD 7 was 0.683 (95 % CI 0.481–0.886) with an optimal threshold of 0.94 mg/dL, sensitivity of 50 % and specificity of 92 % and the diagnostic accuracy was poor." (PMID 26530188, 2015). "The further multiple logistic regression analyses of the ten significant variables revealed that three variables were independent risk factors for the development of hypoalbuminemia: APACHE II score, CRP, and blood lactate." (PMID 26557421, 2015). "Biochemical parameters used with CRP (specifically in renal cell carcinoma) were: albumin (alone or as hypoalbuminemia), LDH, and interleukins (IL-6, IL-8, IL-2)." (PMID 26717416, 2015). "We consider that hypoalbuminemia resulted from increased CRP, which can be explained by the following: inflammatory cytokines decrease the synthesis of constitutive proteins, such as serum albumin, and increase its degradation." (PMID 26530188, 2015). "CRP also demonstrated a convincing predictive value of hypoalbuminemia, as evidenced by AUC of 0.842 (P < 0.001), and its optimal cut-off point was 34.25 mg/L." (PMID 26557421, 2015). "According to the mGPS, 31 (18.5%) patients had both hypoalbuminemia and high CRP levels (mGPS = 2), 77 (16.4%) patients had high CRP levels but normal albumin (mGPS = 1), and the remaining 360 (76.9%) patients had neither risk factor (mGPS = 0)." (PMID 26390126, 2015). "The AUC of CRP on POD 3 to development of hypoalbuminemia on POD 7 was 0.833 (95 % CI 0.679–0.987) with an optimal threshold of 12.43 mg/dL, sensitivity of 75 % and specificity of 80 %, and the diagnostic accuracy was good." (PMID 26530188, 2015). "Recent studies showed that some blood parameters associated with systemic inflammation, i.e. C-Reactive Protein (CRP), white cell, neutrophil and platelet count, and hypoalbuminemia are predictors of survival in patients with primary solid cancers." (PMID 25886534, 2015). "The area under the receiver operating characteristic curve of CRP on POD 3 to development of hypoalbuminemia on POD 7 was 0.833 (95 % CI 0.679–0.987) with an optimal threshold of 12.43 mg/dL, sensitivity 75 % and specificity 80 %." (PMID 26530188, 2015). "The most common clinical findings of dogs with Rickettsia infection diagnosed by seroconversion and/or PCR were fever, myalgia, lameness, elevation of C-reactive protein, thrombocytopenia and hypoalbuminemia." (PMID 25886403, 2015). "Among the several methods used to measure systemic inflammation, the NLR and PLR are the most used parameters in conjunction with the Glasgow Prognostic Score (GPS) that takes into account hypoalbuminemia and elevation of C-reactive protein (CRP)." (PMID 24409281, 2014). "Among the 343 patients, 48 (14.0 %) had an elevated CRP level (>10 g/L) and 29 (8.5 %) had hypoalbuminemia (<35 g/L)." (PMID 24452408, 2014). "Thirty one (20.7%) patients showed an elevated CRP level (>1.0 g/dl) and 58 (38.7%) patients had hypoalbuminemia (<3.5 g/dl)." (PMID 23374755, 2013). "Multivariate analysis demonstrated that elevated serum CRP levels, age >60 years, hypoalbuminemia, and elevated lactate dehydrogenase levels were independent adverse predictors of OS." (PMID 23724031, 2013). "Over the past decade, the relationship between inflammation markers (e.g. an elevated CRP level), malnutrition (e.g. hypoalbuminemia), and mortality has received much attention." (PMID 24007461, 2013). "The result indicated that old age, male gender, hypoalbuminemia, elevated baseline high-sensitive CRP, large ultrafiltration volume, high CT ratio, and average postdialysis SBP rise of more than 5 mmHg were independent predictors of 4-year all-cause mortality." (PMID 22414233, 2012). "In critical illness, hypoalbuminemia and hypoprealbuminemia are very common and inversely related to C-reactive protein." (PMID 22554240, 2012).
Hypoalbuminemia (continued). "A total of 68 patients (54.4%) had an elevated CRP level (>1 mg/dl) and 38 patients (30.4%) had hypoalbuminemia (<3.5 mg/dl)." (PMID 23170106, 2012). "A total of 140 patients (34.9%) had an elevated CRP concentration (> 1 mg/dL), and 77 patients (19.2%) had hypoalbuminemia (< 3.5 mg/dL)." (PMID 22103888, 2011). "Further analysis revealed that those factors are lymphocytopenia, hypoalbuminemia, and increased CRP levels." (PMID 21513568, 2011). "A study done to evaluate if CRP and serum albumin were survival predictors of esophageal cancer demonstrated that only serum CRP concentration and hypoalbuminemia were independent prognostic indicators of survival." (PMID 21176210, 2010). "Of the 40 patients with hypoalbuminaemia, 31 (78%) had an elevated C-reactive protein concentration." (PMID 19209171, 2009). "This specific feature of high-serum CRP concentration and hypoalbuminemia in some myeloma patients has been addressed earlier with regard to disease activity." (PMID 16969356, 2006). "Of the 52 patients with hypoalbuminaemia, 45 (86%) had an elevated C-reactive protein concentration." (PMID 16479253, 2006). "On univariate analysis, an elevated C-reactive protein (P<0.01), hypoalbuminaemia (P<0.05), the GPS (P<0.001) and treatment (P<0.05) were associated with poor cancer-specific survival." (PMID 16404432, 2006). "The relationship between hypoalbuminaemia, tumour volume and C-reactive protein was examined in patients with colorectal liver metastases (n=57)." (PMID 15213726, 2004). "Approximately 50% had stage III disease, 90% had an ECOG performance status of 0–1, 75% had an elevated C-reactive protein and 10% had hypoalbuminaemia." (PMID 15150622, 2004). "Patients with hypoalbuminaemia had significantly higher concentrations of bilirubin (P=0.034) and C-reactive protein (P=0.006)." (PMID 15213726, 2004). "The aim of the present study was to assess the value of combining C-reactive protein and recognised prognostic factors as stage, performance status and hypoalbuminaemia to form new prognostic scores for patients with inoperable NSCLC." (PMID 12966420, 2003). "They rarely have nephrotic range proteinuria but the level of hypoalbuminaemia together with raised C-reactive protein may reflect the severity of the ongoing active inflammatory process." (PMID 39927255, 2025). "Additionally, a close relationship has been identified between the increase in CRP and hypoalbuminemia." (PMID 40802406, 2025). "Hypoalbuminemia may decrease oncotic pressure and intravascular volume, while elevated CRP levels reflect chronic systemic inflammation, which may affect vascular reactivity and endothelial function." (PMID 41257946, 2025). "In many instances, locally produced IL-6 entered the peripheral circulation and caused systemic effects such as cachexia and tumor-associated syndromes (fever, increased erythrocyte sedimentation rate, increased serum C-reactive protein levels, hypoalbuminemia)." (PMID 40549756, 2025). "Additionally, mild transaminitis was present, along with hypoalbuminemia and an elevated C-reactive protein (CRP) level." (PMID 40895922, 2025). "Indeed, in our study, there was a stronger correlation between hypoalbuminemia and inflammatory parameters, such as CRP (Pearson's r = −.45), than to body mass index (r = .16) or degree of hepatic involvement (point biserial correlation coefficient rpb = .26)." (PMID 38477040, 2025). "We also skipped assessing inflammation indicators like C-reactive protein or interleukin-6, which could clarify ties among hypoalbuminemia, albuminuria, and CVDs." (PMID 41536368, 2025). "The observed hypoalbuminemia may result from systemic inflammation (as evidenced by elevated CRP), increased vascular permeability due to pertussis toxin, or a catabolic state caused by prolonged illness and poor oral intake." (PMID 40539153, 2025).
Hypoalbuminemia (continued). "Using a different prognostic scoring system based on presence of markers of systemic inflammation (the modified Glasgow Prognostic Score (mGPS)), 24% had an intermediate score 1 (CRP levels > 10 mg/L) but only 13% had the worst prognostic score 2 (elevated CRP and hypoalbuminemia)." (PMID 40325598, 2025). "Hypoalbuminemia (<3.8 g/dL) and elevated high-sensitivity CRP (>3 mg/L) are common markers." (PMID 41516280, 2025). "Other laboratory test findings may reveal hypoalbuminemia, hypergammaglobulinemia, hypertransaminasemia, and elevated markers of inflammation, such as C-reactive protein (CRP) and erythrocyte sedimentation rate." (PMID 40423365, 2025). "Therefore, early assessment of malnutrition, including hypoalbuminemia, hypocholesterolemia, low lymphocyte counts, and CRP, is more conducive to early prediction of inflammatory factor storm after CAR-T therapy in r/r AML patients." (PMID 40686821, 2025). "After adjusting for confounders, the risk of low HDL-C remained significantly increased by 2.284 times in patients with severe infections, 2.820 times in those with fever, 1.759 times in those with high CRP, and 2.648 times in those with hypoalbuminemia (all Ps< 0.05)." (PMID 40607030, 2025). "Patients with severe infections (0.94 mmol/L), heart failure (1.025 mmol/L), chronic kidney disease (1.03 mmol/L), fever (0.85 mmol/L), high CRP levels (1.01 mmol/L), and hypoalbuminemia (0.91 mmol/L) had significantly lower HDL-C levels compared to those without these conditions." (PMID 40607030, 2025). "Similarly, the mean CRP level was 180 mg/l ± 114.137 in patients with hypoalbuminemia compared to 116 mg/l ± 99.374 in those with normal albumin levels (P < 0.001)." (PMID 39048942, 2024). "At admission and during the first days of the hospital stay, the child’s condition was stable but impaired with remarkably high inflammatory markers (C-reactive protein, procalcitonin, interleukin—6, ferritin, D-dimer), with hypoalbuminemia, peripheral edemas, and skin rash." (PMID 39449398, 2024). "Hence, it is of interest that the combination of hypoalbuminemia (<3.5 g/dL) and an elevated CRP (>1.0 mg/dL) level, used to calculate the Glasgow prognostic score (GPS), the modified GPS (mGPS), and high-sensitivity mGPS, is an important indicator." (PMID 38473433, 2024). "Furthermore, we also identified that the presence of liver metastasis, surrogate markers of cachexia (hypoalbuminemia and elevated basal CRP levels) and bedside ECOG-PS assessment upon ICU admission were also predictors of mortality." (PMID 38611643, 2024). "The development of a systemic inflammatory response in cancer patients is characterized by elevated CRP and hypoalbuminemia, which has a substantial impact on survival due to accelerated protein breakdown and direct catabolic effects on skeletal muscles and other host tissues." (PMID 39000088, 2024). "Additionally, the clinical and biochemical markers of cachexia (hypoalbuminaemia, high CRP, worse performance status) were each correlated with lower noroxycodone concentrations or its metabolic ratio." (PMID 39628313, 2024). "However, hypoalbuminemia alone is rare, and few patients exhibit hypoalbuminemia when CRP levels are normal." (PMID 39464717, 2024). "The competing risk model analysis indicated a higher cumulative incidence of TSM in patients with advanced age (p = 0.003), underweight (p = 0.024), retreatment (p < 0.001), cavities on CXR (p < 0.001), hypoalbuminemia (p < 0.001) and CRP ≥ 10 mg/L (p = 0.002)." (PMID 39882120, 2024). "Absence of glomerular IgG4 deposition, together with older age, severe hypoalbuminemia and high serum CRP level, could be useful clues to differentiate cancer-related MN from idiopatic MN." (PMID 37190182, 2023). "An elevated HS-mGPS is indicative of a patient with hypoalbuminemia, a high CRP level, or both." (PMID 36674837, 2023).
Hypoalbuminemia (continued). "Regarding analytical parameters, those patients who developed HF had worse renal function, lower oxygen saturation, higher CRP, D-dimer, leukocytes, glycemia, potassium, and procalcitonin values, as well as lower pH values, lower platelet count or hypoalbuminemia more frequently." (PMID 37510764, 2023). "The CRP to albumin ratio (high CRP and hypoalbuminemia), reflecting prolonged exhaustion owing to inflammation, may be a potential prognostic factor in patients with cancer." (PMID 37073452, 2023). "In addition to the elevation of CRP, hypoalbuminemia also indicates an inflammatory status, which is related to a decrease in muscle mass and an increase in extracellular volume in patients." (PMID 37386392, 2023). "While determination of serum-cholinesterase does not have any diagnostic value, it has been established that hypoalbuminemia alone or accompanied by an increase in creatinine, lactate, or C-reactive protein serum levels has negative prognostic value." (PMID 37047631, 2023). "Children with hyponatremia had higher CRP and hypoalbuminemia, both markers for inflammation, as compared to eunatremic patients which may suggest potentiation of inflammation and in some, SIADH." (PMID 37744432, 2023). "In oncological malignancies, biochemical and hematological markers were used to assess the impact of the systemic inflammatory response on outcomes such as increased C-reactive protein (CRP) concentration, increased white cell, neutrophil, and platelet counts, and hypoalbuminemia." (PMID 36819360, 2023). "Also, the markers of the systemic inflammatory response (such as plasma C-reactive protein (CRP) or hypoalbuminemia) have been shown to play a major role in cancer progression and aggressiveness." (PMID 37283751, 2023). "In many circumstances, locally produced IL-6 reached the peripheral circulation and elicited systemic effects such as cachexia and paraneoplastic syndrome (including fever, increased erythrocyte sedimentation rate, increased levels of C-reactive protein in serum, hypoalbuminemia)." (PMID 35406728, 2022). "Systemic inflammation, detectable through increased levels of C-reactive protein, cytokines, leukocytes, and their subtypes and hypoalbuminemia, was detected in our study with increased NLR and RDW values, which can be induced by the inflammatory response of the tumour microenvironment." (PMID 36077723, 2022). "However, studies have demonstrated that hypoalbuminemia and elevated CRP levels are important predictors of death in patients with HF in some scenarios." (PMID 36185864, 2022). "The major difference between the GPS and mGPS is the risk classification of patients with hypoalbuminemia without an increased CRP levels; these patients are considered an intermediate-risk group in GPS (GPS 1), while they are at low risk in mGPS (mGPS 0)." (PMID 36079741, 2022). "This systemic IL-6 spillover is considered a basis for paraneoplastic syndrome, which includes cachexia (loss of body weight), fever, enhanced erythrocyte sedimentation rate, and altered acute phase plasma protein levels (e.g., enhanced C-reactive protein levels and hypoalbuminemia)." (PMID 35406728, 2022). "Although mGPS can be a useful prognostic biomarker in patients with HNC in various clinical scenarios, mGPS classification showed results similar to GPS, and the systemic inflammation indicated by CRP levels led to escalated protein breakdown and subsequent hypoalbuminemia." (PMID 36079741, 2022). "The mGPS scoring system is classified according to C-reactive protein (CRP) levels as follows: score 0 for patients with CRP <10 mg/L without high-serum albumin levels, score 1 for patients with CRP (>10 mg/L), and score 2 for CRP (>10 mg/L) with hypoalbuminemia (<3.5 g/dL)." (PMID 36291803, 2022).
Hypoalbuminemia (continued). "After exclusion of patients with bone metastatic disease, both hypoalbuminemia and high CRP were associated with a negative bone turnover (CTX/Ocn: OR 10.5 for hypoalbuminemia and OR 7.6 for high CRP; CTX/PINP: OR 7.7 for high CRP; p ≤ 0.01)." (PMID 34182958, 2021). "Moreover, the survival outcomes of patients with hypoalbuminemia alone were significantly better than patients with elevated CRP levels, indicating that CRP played a more important role in survival prediction." (PMID 34221991, 2021). "Hypoalbuminemia or a high Kyn/Trp ratio (CCES 1) was significantly associated with advanced stage of the disease at diagnosis, an ECOG (Eastern Cooperative Oncology Group) performance status of ≥1, presence of ascitic fluid, and high CRP plasma levels." (PMID 34884980, 2021). "Whilst raised CRP and hypoalbuminaemia occur commonly in cancer patients, it may limit the usefulness as a prognostication tool." (PMID 34400804, 2021). "The “unexpected” outcome might be attributed to the asynchronous pathogenesis process and change in time of CRP and hypoalbuminemia during the acute process of KD." (PMID 33712036, 2021). "Most patients had abnormally high levels of WBCs and CRP but hypoalbuminemia in 76.2%." (PMID 33025538, 2021). "Hypoalbuminemia is a feature of inflammation as confirmed in our study by the inverse relation between albumin and CRP or IL-6, but it might also the consequence of a high clearance of oxidized form of albumin." (PMID 34299080, 2021). "Severe hypoalbuminemia and markedly elevated C-reactive protein were related to inadequate PC." (PMID 34200506, 2021). "It has been reported that patients had different probabilities of disease progression based on age, residence in nursing home, comorbidities, obesity, respiratory rate and presence of respiratory symptoms, fever, lymphocyte count, troponin level, CRP level, and hypoalbuminemia." (PMID 33925831, 2021). "A high CRP score may indicate an elevated serum CRP concentration in conjunction with hypoalbuminemia, an elevated CRP concentration relative to normal Alb levels, or normal CRP concentrations relative to a depressed Alb concentration." (PMID 33686103, 2021). "During hospitalization, abnormal laboratory values were typical, such as elevated erythrocyte sedimentation rate (ESR) (50%), hypoalbuminemia (63.6%), hypocalcemia (40.2%), leucocytosis (51.4%), abnormal liver function (16.4%), hyperlipidemia (19.1%), and elevated hypersensitive CRP (90%)." (PMID 34018629, 2021). "In addition, they show that variability of the drug remains high despite the 2012 updated dosing recommendations, and that voriconazole levels are influenced by severe hypoalbuminemia and elevated CRP." (PMID 34200506, 2021). "Since the GPS reflects systemic inflammation (elevated CRP) and malnutrition (hypoalbuminemia), it may be considered appropriate to reflect the severity of HF." (PMID 34294776, 2021). "Its prognostic role has been well defined in more advanced stage of disease, where the boosted inflammatory response, usually revealed by increased level of C-reactive protein and hypoalbuminemia, can promote tumor growth through the production of cytokines and growth factors." (PMID 34359855, 2021). "In this study, unlike β2MG, elevated AG was significantly associated with high CRP level, but not hypoalbuminemia." (PMID 33019590, 2020). "The low serum creatinine together with hypoalbuminemia, higher CRP and ferritin found in PAD patients might reflect low muscle mass or frailty of patients and chronic inflammation in patients on dialysis." (PMID 31950864, 2020). "Elevated ESR, CRP, and liver transaminases and were also found in addition to hypoalbuminemia." (PMID 33167916, 2020).